TOB1 (transducer of ERBB2, 1)
Description:
Anti-proliferative protein; the function is mediated by association with deadenylase subunits of the CCR4-NOT complex. Mediates CPEB3-accelerated mRNA deadenylation by binding to CPEB3 and recruiting CNOT7 which leads to target mRNA deadenylation and decay.
Synonyms: TOB; TROB1; TROB; APRO5; APRO6; PIG49
Tractability: Small molecule: a structure with a bound ligand is known. PROTAC: ubiquitination databases record sites on it.
Gene: Protein-coding gene on chromosome 17 (50,862,223 to 50,867,978, reverse strand). Ensembl gene ENSG00000141232.
Subcellular location: Cytoplasm; Nucleus
Subcellular location (Human Protein Atlas): Nucleoplasm; Vesicles
Gene Ontology:
Molecular function: protein binding; receptor tyrosine kinase binding; transcription corepressor activity; SMAD binding
Biological process: negative regulation of cell population proliferation; negative regulation of nuclear-transcribed mRNA poly(A) tail shortening; negative regulation of translation; positive regulation of nuclear-transcribed mRNA catabolic process, deadenylation-dependent decay; positive regulation of nuclear-transcribed mRNA poly(A) tail shortening; regulation of gene expression; negative regulation of DNA-templated transcription
Cellular component: CCR4-NOT complex; cytoplasm; nucleus
Genetic constraint (gnomAD): Loss-of-function variants: 2 observed, 23.67 expected, observed/expected ratio (o/e) 0.0845, 90% interval 0.034 to 0.27. The upper end of that interval is the gene's LOEUF score, 0.27, which puts it in group 1 of 6, group 1 being the genes least tolerant of losing a copy. Missense variants: 299 observed, 442.72 expected, observed/expected ratio (o/e) 0.68, 90% interval 0.61 to 0.74. Synonymous variants: 154 observed, 158.49 expected, observed/expected ratio (o/e) 0.97, 90% interval 0.85 to 1.11.
Homologues: Orthologues: chimpanzee TOB1 (100% identical), macaque TOB1 (100% identical), dog TOB1 (99% identical), rabbit TOB1 (99% identical), rat Tob1 (97% identical), mouse Tob1 (97% identical), guinea pig TOB1 (96% identical), zebrafish tob1a (79% identical), zebrafish tob1b (77% identical), tropical clawed frog tob1 (70% identical), Drosophila melanogaster Tob (46% identical), Caenorhabditis elegans fog-3 (20% identical), and 1 more. Paralogues in human: TOB2 (58% identical).
Diseases named in the same sentence as TOB1 in open-access papers:
TOB1 is named in the same sentence as 63 diseases in open-access papers, as found by Europe PMC text mining. Sharing a sentence is not in itself a finding about the gene and the disease. The quoted sentences say what the papers report.
gastric cancer (17 papers, 2012 to 2025). A primary or metastatic malignant neoplasm involving the stomach. "Further exploration of the role of TOB1 in neutrophils in gastric cancer and its association with immunotherapy." (PMID 38617839, 2024). "In contrast, in gastric cancer tissues, lower TOB1 levels were strongly associated with immune cell infiltration." (PMID 38617839, 2024). "An elevated ratio of p-TOB1 was associated with functional inactivation of the TOB1 gene in gastric cancer." (PMID 35186488, 2022). "Consistently, the downregulation of Tob1 is associated with the shorter survival of gastric cancer patients." (PMID 36230852, 2022). "Moreover, high expression of phosphorylated TOB1 in the cell nucleus of patients with intestinal-type gastric cancer is associated with poor prognosis." (PMID 38617839, 2024). "Moreover, decreased expression levels of DAL-1 and TOB1 were associated with shorter survival of gastric cancer patients." (PMID 35186488, 2022). "This study is aimed at verifying whether overexpressing TOB1 induces autophagy by secreting exosomes in gastric cancer cells and its underlying mechanisms." (PMID 35465266, 2022). "However, the role of Tob1 in the migration and invasion of gastric cancer cells and its underlying mechanisms are yet to be investigated." (PMID 22710759, 2012). "The present study aimed to investigate whether Tob1 could inhibit gastric cancer progression in vitro, and to elucidate its underlying molecular mechanisms." (PMID 22710759, 2012). "Similarly, the downregulation of Tob1 may be associated with the shorter survival of gastric cancer patients." (PMID 36230852, 2022). "Thus, we attempted to investigate whether ectopic expression of Tob1 could inhibit gastric cancer progression and to elucidate its underlying mechanisms." (PMID 22710759, 2012). "The findings indicate that TOB1 potentially extends the survival of gastric cancer patients by fostering the anti-tumor polarization of neutrophils, restraining their apoptosis, and augmenting patients’ responsiveness to immunotherapy." (PMID 38617839, 2024). "Survival analysis was performed using the R package survminer to calculate cutoff values to explore the potential impact of immune cell infiltration and TOB1 expression levels in immune cells on the prognosis of patients with gastric cancer." (PMID 38617839, 2024). "Our research group previously discovered that TOB1 functions as a tumor suppressor in gastric cancer." (PMID 38617839, 2024). "For instance, studies have found that TOB1 expression is downregulated in breast cancer, lung cancer, and gastric cancer, and its overexpression can inhibit tumor cell proliferation and induce apoptosis." (PMID 38617839, 2024). "This study employed multiplex immunofluorescence analysis to precisely delineate and quantify the expression of TOB1 in immune cells within gastric cancer tissue microarrays." (PMID 38617839, 2024). "A total of 415 tissue samples from patients with gastric cancer were used to analyze TOB1 expression in immune cells, and the deconvolution algorithms CIBERSORT and quanTIseq from the GEPIA2021 website were used." (PMID 38617839, 2024). "The ErbB-2.1(TOB1) signaling transducer protein is a tumor-suppressive protein that actively suppresses the malignant phenotype of gastric cancer cells." (PMID 38617839, 2024). "To further elucidate the mechanistic implications of TOB1 on the prognosis of gastric cancer patients, we compiled data from a cohort of 374 individuals with gastric cancer, sourced from the TCGA and TIMER2 databases." (PMID 38617839, 2024). "Phosphorylated TOB1 is an inactivated form, and our group revealed that phosphorylation of TOB1 at threonine 172 and serine 320 promotes aggressive phenotypes in gastric cancer." (PMID 38617839, 2024). "The results showed varying levels of TOB1 expression among different immune cells in gastric cancer, with a particularly noticeable pattern observed using the CIBERSORT algorithm." (PMID 38617839, 2024).
gastric cancer (continued). "Understanding the expression and role of TOB1 in the gastric cancer immune environment is crucial to maximize its potential in targeted immunotherapy." (PMID 38617839, 2024). "TOB1 expression in peripheral blood neutrophils and peripheral blood mononuclear cells (PBMCs) from 31 patients with gastric cancer and 43 healthy individuals was analyzed." (PMID 38617839, 2024). "Among the six immune cell types, TOB1 displayed the highest correlation with CD8+ T cells in gastric cancer tissues (R = 0.66 and R = 0.76)." (PMID 38617839, 2024). "In both patients with gastric cancer (P < 0.001) and healthy controls (P < 0.001), TOB1 mRNA expression in neutrophils was significantly higher than that in PBMCs." (PMID 38617839, 2024). "In gastric cancer, the anti-tumor function of TOB1 is not only manifested through anti-proliferation but also involves inducing tumor cell autophagy." (PMID 38617839, 2024). "In gastric cancer, TOB1 inhibits tumor cell proliferation, invasion, and migration while promoting autophagy, suggesting its potential as a therapeutic target for cancer treatment." (PMID 38617839, 2024). "This study significantly advances our comprehension of TOB1’s role within the immune microenvironment of gastric cancer, offering promising therapeutic targets for immunotherapy in this context." (PMID 38617839, 2024). "For example, the low TOB1 expression activates gastric cancer progression by inhibiting Smad4- and activating β‐catenin-mediated signaling pathways." (PMID 38062199, 2023). "Here, our study provides further evidence that exosomes secreted by gastric cancer cells overexpressing TOB1 can induce autophagy in gastric cancer cells." (PMID 35465266, 2022). "We found that the conversion of LC3-I to LC3-II was significantly increased in gastric cancer cells 48 h after overexpressing TOB1." (PMID 35186488, 2022). "The latest study of our group confirmed that TOB1 can induce autophagy in gastric cancer cells via decreasing the activation of AKT/mTOR signaling pathway." (PMID 35465266, 2022). "Subsequently, our group has successively demonstrated that TOB1 is downregulated and phosphorylated in gastric cancer tissues, and TOB1 plays an antiproliferative role in the nucleus and a series of studies." (PMID 35465266, 2022). "The increase in the LC3-II/LC3-I ratio reflected the potentiation of autophagy, which was maintained for 72 h after overexpressing TOB1 in gastric cancer cells." (PMID 35186488, 2022). "In order to explore the relationship between TOB1-induced autophagy and exosomes in gastric cancer cells, we selected gastric cancer cell lines overexpressing exogenous TOB1 (AGS-TOB1) and knocking out TOB1 (HGC-27-TOB1-6E12)." (PMID 35465266, 2022). "In order to further confirm that exosomes secreted by gastric cancer cells overexpressing TOB1 can induce autophagy in gastric cancer cells, we observed the ultrastructure of gastric cancer cells by TEM to find autophagosomes." (PMID 35465266, 2022). "In conclusion, the current results strongly confirm that gastric cancer cells overexpressing TOB1 gene induce autophagy by secreting exosomes." (PMID 35465266, 2022). "To dynamically observe the effect of TOB1 expression on autophagy in gastric cancer cells, we used a two-color fluorescent GFP-RFP-LC3 fusion protein to trace the process of autophagy." (PMID 35186488, 2022). "The results showed that p-AKT levels were significantly decreased in gastric cancer cells overexpressing TOB1 compared with control cells (*P = 0.0459), indicating that overexpression of the TOB1 gene can inhibit AKT phosphorylative activation." (PMID 35186488, 2022). "We transiently overexpressed TOB1 in gastric cancer AGS cells and performed immunoblotting to determine the effect on LC3 protein." (PMID 35186488, 2022). "Through transmission electron microscopy, we observed that autophagosomes were more common in gastric cancer cells with TOB1 overexpression than in control cells." (PMID 35186488, 2022).
gastric cancer (continued). "The increased incidence of gastric cancer is also correlated with the inactivation of tumor suppressor genes, including TOB1 on chromosome 17." (PMID 26694352, 2015). "Recent studies demonstrated that loss of TOB1 facilitates migration and invasion of human lung cancer and gastric cancer cells, indicating the role of TOB1 in suppressing tumor progression." (PMID 26694352, 2015). "This study reported that TOB1 expression was either abolished or reduced in 75% of patients with gastric cancer." (PMID 26694352, 2015). "Our results showed that Tob1 induced Bax expression and inhibited Bcl-2 expression in gastric cancer cells." (PMID 22710759, 2012). "Here, we report for the first time that ectopic expression of Tob1 induces apoptosis and inhibits the proliferation of gastric cancer cells in vitro." (PMID 22710759, 2012). "We first examined the expression of Tob1 in a variety of gastric cancer cells including MKN28, AGS, and MKN1." (PMID 22710759, 2012). "The inhibition of cell viability by ectopic expression of Tob1 prompted us to examine if Tob1 overexpression can induce apoptosis in gastric cancer cells." (PMID 22710759, 2012). "Collectively, our study demonstrates that the overexpression of Tob1 inhibits gastric cancer progression by activating Smad4- and inhibiting β-catenin-mediated signaling pathways." (PMID 22710759, 2012). "Transducer of ErbB-2.1 (Tob1), a tumor suppressor protein, is inactivated in a variety of cancers including stomach cancer." (PMID 22710759, 2012). "Consequently, a comprehensive understanding of TOB1 expression and function within the gastric cancer immune microenvironment is warranted." (PMID 38617839, 2024). "Interestingly, a significant upregulation of TOB1 mRNA in neutrophils was observed in gastric cancer patients when compared to the healthy control group (P < 0.001)." (PMID 38617839, 2024). "Overall, TOB1 plays a crucial role in the anti-tumorigenic processes in gastric cancer." (PMID 38617839, 2024). "This suggests that TOB1 knockdown may contribute to the development of neutrophils into a phenotype that promotes gastric cancer." (PMID 38617839, 2024). "TOB1 is a gene that exerts a negative regulatory effect on the progression of gastric cancer and holds a significant position with potential as a novel target in targeted gastric cancer therapy." (PMID 38617839, 2024). "Two TMA slides, each containing 90 pairs of gastric cancer and corresponding paracancerous tissues, were selected for mIF analysis of TOB1, CD8, CD4, FOXP3, CD20, CD68, and CD66b to investigate the profiles of TOB1 protein expression and immune cell infiltration in gastric cancer." (PMID 38617839, 2024). "In our study, gastric cancer patients with the high level TOB1 in neutrophils group may be more likely to benefit from immunotherapy." (PMID 38617839, 2024). "However, understanding the role of TOB1 in the immune microenvironment of gastric cancer is crucial for targeted therapy." (PMID 38617839, 2024). "In addition, western blot data revealed that high TOB1 protein levels were associated with the formation of autophagosomes by suppressing the phosphorylation activation of AKT and mTOR in gastric cancer cells." (PMID 35186488, 2022). "At present, previous studies of our group have revealed that the overexpression of TOB1 can induce autophagy in gastric cancer cells, and its mechanism may be related to the down-regulation of Akt/mTOR signaling pathway." (PMID 35465266, 2022). "Our results provide direct evidence of TOB1-induced autophagy in gastric cancer cells." (PMID 35186488, 2022). "In addition, the functional miRNAs in the exosomes secreted by gastric cancer cells overexpressing TOB1 need to be further explored to provide more candidate molecules for tumor diagnosis and treatment." (PMID 35465266, 2022).
gastric cancer (continued). "The data showed that compared with the control cells, the TOB1-overexpressing gastric cancer cells had a significantly reduced content of p-mTOR (**P = 0.0011), indicating that overexpression of the TOB1 gene may inhibit the phosphorylative activation of mTOR." (PMID 35186488, 2022). "The purpose of this study was to explore whether TOB1 induces autophagy through the AKT/mTOR signaling pathway in gastric cancer." (PMID 35186488, 2022). "Our group has demonstrated that TOB1 is a tumor suppressor in gastric cancer." (PMID 35186488, 2022). "Our results provide novel insight that TOB1 might suppress gastric cancer by inducing autophagy, possibly through decreasing phosphorylation and the subsequent activation of the AKT/mTOR signaling pathway." (PMID 35186488, 2022). "Clarification of these remaining unknowns will provide a reliable foundation for using TOB1 as a biomarker to improve therapeutic efficacy in patients with gastric cancer." (PMID 35186488, 2022). "To confirm the effect of TOB1 on autophagy in gastric cancer cells, we selected the gastric cancer cell line AGS, which expresses low levels of endogenous TOB1 protein, and transiently transduced these cells with GV358-TOB1 lentivirus or empty GV358 vector lentivirus (as a control)." (PMID 35186488, 2022). "We revealed that LC3 puncta formation in gastric cancer cells could be induced and further potentiated following TOB1 overexpression, indicating that the TOB1 gene can induce autophagy in gastric tumor cells." (PMID 35186488, 2022). "Altogether, the present results strongly support our hypothesis that TOB1 promotes autophagy in gastric cancer cells." (PMID 35186488, 2022). "We previously identified the tumor suppressor gene TOB1 as related to gastric cancer." (PMID 35186488, 2022). "Previous study of our group first revealed that TOB1 is a gastric cancer-related tumor suppressor." (PMID 35465266, 2022). "Moreover, at 72 h, significantly more LC3 puncta were present in gastric cancer cells transduced with TOB1 lentivirus than in control cells, indicating that overexpression of the TOB1 gene can induce autophagy in gastric cancer cells." (PMID 35186488, 2022). "Exosomes secreted from gastric cancer cells overexpressing Tob1 could induce autophagy of LC3-II accumulation in the gastric cancer cells, which may influence the proliferation, migration, and invasion of cancer cells." (PMID 36230852, 2022). "Accumulating evidence suggests that the activation of TOB1 may induce autophagy in gastric cancer through the AKT pathway." (PMID 35186488, 2022). "Our study hypothesized that the dysregulated RNA in the exosomes of gastric cancer cells overexpressing TOB1 might be transported to gastric cancer cells through the exosomal pathway to exert its biological role." (PMID 35465266, 2022). "The downregulated expression of Tob1 has been found in malignant gastric cancer, suggesting that the low expression of Tob1 may be an independent indicator of poor prognosis in gastric cancers." (PMID 36230852, 2022). "Overexpression of Tob1 in gastric cancer cell lines induced the expression of Smad4 and p15." (PMID 32375405, 2020). "This difference in the estimated expression status of TOB1-2 has potentially important biological implications because TOB1 is a tumor suppressor, and in gastric cancer cells, miR-25 represses TOB1 by binding to a 3′-UTR region that is present in TOB1-1 but absent in TOB1-2." (PMID 27405803, 2016). "We also reported that TOB1 overexpression in human gastric cancer (MKN28 and AGS) cells restored the levels of SMAD4 and increased the promoter activity and the mRNA and protein level of its target gene CDKN2B (P15(INK4B)), thereby inducing cell cycle arrest and apoptosis." (PMID 26694352, 2015). "The LOH of TOB1 was also detected in human gastric cancer specimens." (PMID 26694352, 2015).